CD200R1L (CD200 receptor 1 like)
Description:
May be a receptor for the CD200/OX2 cell surface glycoprotein.
Synonyms: CD200RLa; CD200R2
Tractability: Antibody: UniProt predicts a signal peptide or a membrane-spanning region.
Gene: Protein-coding gene on chromosome 3 (112,815,709 to 112,846,864, reverse strand). Ensembl gene ENSG00000206531.
Subcellular location: Membrane
Gene Ontology:
Molecular function: protein binding; signaling receptor activity
Biological process: regulation of neuroinflammatory response
Cellular component: external side of plasma membrane; cell surface; membrane
Genetic constraint (gnomAD): Loss-of-function variants: 9 observed, 19.23 expected, observed/expected ratio (o/e) 0.47, 90% interval 0.28 to 0.82. The upper end of that interval is the gene's LOEUF score, 0.82, which puts it in group 3 of 6, group 1 being the genes least tolerant of losing a copy. Missense variants: 257 observed, 263.67 expected, observed/expected ratio (o/e) 0.97, 90% interval 0.88 to 1.08. Synonymous variants: 92 observed, 95.87 expected, observed/expected ratio (o/e) 0.96, 90% interval 0.81 to 1.14.
Homologues: Orthologues: chimpanzee CD200R1L (97% identical), macaque CD200R1L (83% identical), pig CD200R1 (52% identical), mouse Cd200r2 (48% identical), mouse Cd200r4 (48% identical), rat Cd200r1l (48% identical), rat Cd200r1 (46% identical), mouse Cd200r1 (44% identical), mouse Cd200r3 (34% identical), tropical clawed frog XB5962421 (29% identical), tropical clawed frog cd200r1 (26% identical). Paralogues in human: CD200R1 (73% identical).
Diseases named in the same sentence as CD200R1L in open-access papers:
CD200R1L is named in the same sentence as 6 diseases in open-access papers, as found by Europe PMC text mining. Sharing a sentence is not in itself a finding about the gene and the disease.
CD200R1L shares sentences with these, for which no sentence is quoted: Alzheimer disease (1 paper); Crohn disease (1); infectious disease (1); psoriasis (1); rheumatoid arthritis (1); Stroke (1).